FOXP3 (forkhead box P3)
Diseases named in the same sentence as FOXP3 in open-access papers (continued):
Sharing a sentence is not in itself a finding about the gene and the disease.
tumor (continued). "We found that 30–40% of tumor-infiltrating CD4 T cells were Treg cells expressing the canonical lineage-specific transcription factor FoxP3 across tested tumor models, suggesting that a high frequency of Treg cells is a general characteristic of CNS tumors." (PMID 33976133, 2021). "The authors stated that the high density of forkhead box P3 (FOXP3)+ Tregs in the TME correlated strongly with early tumor recurrence." (PMID 34282055, 2021). "As for cancer, thymically derived natural Treg cells were suggested as the primary type of Treg cells in tumor tissues and showed a conserved demethylated region in the first intron of the FOXP3 gene." (PMID 34177907, 2021). "Immune cell characterization revealed the overall prevalence of FOXP3+ cells and pro-tumor M2-like macrophages." (PMID 34799669, 2021). "The number of FOXP3 positive cells were also inversely correlated with the expression of PD-L1 in the tumor." (PMID 34362334, 2021). "In contrast, during the advanced stages of tumor development (Day 68), the Foxp3+ cells were significantly higher in the tumor-bearing WT mice, compared to the STAT6−/− AOM/DSS animals, (30.6 ± 7.3 vs. 5.6 ± 4.2, p < 0.001)." (PMID 33919941, 2021). "As we found high lymphocyte infiltrates in the tumor margins of a significant number of samples, we next determined if the accumulation of CD3+, CD8+ or FoxP3+ T lymphocytes were associated with any CRC clinical or pathological parameters." (PMID 34440038, 2021). "The study determined that CAF suppression of CD8+ and promotion of FoxP3+ tumor-infiltrating lymphocytes was mediated by IL-6, suggesting IL-6 blockade via CAF targeting as a possibility to enhance the efficacy of immunotherapy in esophageal cancers." (PMID 33808627, 2021). "It has been described that the tumor suppressor activity of FOXP3 is located in the N-terminal region of the protein (Aa 1-196)." (PMID 33671179, 2021). "This was accompanied with a reversal in the zymosan-mediated increase in frequencies of IFN-γ+ Th1 cells, as well as a small but significant increase in the frequency of CD4+Foxp3+ Treg cells primarily in the tumor-draining lymph nodes." (PMID 34127673, 2021). "Analysis of the effect of TEXomiR on the frequency of tumor-infiltrated CD4+CD25+Foxp3+ regulatory T cells was conducted by flow cytometry in a CD4+ T cell population." (PMID 33987190, 2021). "We selected the markers of the immune checkpoint molecule (PD1, PD-L1, and LAG-3) and immune cell (CD3, CD4, CD8, and Foxp3) as markers of the tumor microenvironment." (PMID 34484468, 2021). "Quantification analysis was done on ROIs (n = 10/slide) and different cell populations including CD3+, CD8+, CD163+, FoxP3+, PD-L1+, and CK+ were analyzed in stromal (CK-) and tumor (CK+) areas, respectively." (PMID 33596250, 2021). "A recent elegant model took advantage of tumor-bearing Foxp3-DTR mice to deplete these cells in anti-PD-1 and anti-CTLA-4 treated mice." (PMID 33571254, 2021). "We further examined the expression of known tumor-promoting markers in these immune subpopulations, confirming that CD4_CXCL13, CD4_FOXP3, CD8_CXCL13, CD8_ISG15, Mac_C1QA, Mac_ISG15 and Mac_SPP1 cells were tumor-promoting immune cells." (PMID 35087839, 2021). "PD-1, CD137 and forkhead box P3 (Foxp3) expression was also detected in the tumour infiltrate, with PD-1 being the most notable marker." (PMID 33402737, 2021). "Despite increased CD8+ T cell PD-1, combination with anti-PD-1 did not improve response, indicating that immunosuppression from Tregs and FoxP3+ NKT cells are major contributors to the immunosuppressive tumour microenvironment." (PMID 34359633, 2021). "Tumor RNA-seq, multiplexed imaging and immunohistology staining show high expression of chemokines, as well as recruitment of FOXP3+ Treg and mast cells, in selective tumor regions." (PMID 33436641, 2021).
tumor (continued). "We observed a significant increase in the ratio of ICT-treated tumor-infiltrating CD8+ T cells to FoxP3+ regulatory T-cells compared to the control group, indicating that ICT activated the antitumor response of cytotoxic T lymphocytes." (PMID 33460401, 2021). "The presence of tumor-infiltratingmast cells and the co-localization of FOXP3-positive cells are a likely mechanism oflocalized downregulation of HLA class I molecules by the tumor cells." (PMID 36283004, 2021). "A pan-cancer meta-analysis revealed the heterogeneity of the prognostic roles of FoxP3s among tumor sites and the antitumor role of FoxP3 in HNSCC (OR, 0.69; 95% CI, 0.50~0.95; p < 0.05)." (PMID 35087741, 2021). "Specifically, ENT treatment reduces the frequency of Tregs within the omental tumor mass and ascites, while also downregulating expression of the lineage‐defining transcription factor FoxP3, consistent with reports in other models." (PMID 33369199, 2021). "To find new potential checkpoints, we investigated the cell-cell communications between tumor-promoting immune cells (CD4_CXCL13, CD4_FOXP3, CD8_CXCL13, CD8_ISG15, Mac_C1QA, Mac_ISG15, Mac_SPP1 and cDC3_LAMP3) and the ductal epithelial cells." (PMID 35087839, 2021). "To further illustrate the immune cell profile, we detected the regulatory T cell by immunofluorescence staining of FOXP3 and observed that the Tregs are markedly increased in the BM tumor microenvironment." (PMID 34229299, 2021). "The accumulation of CD8+CD25+FOXP3+ T cells (also known as CD8+ Tregs) has been observed in the tumour microenvironment of several cancers and are thought to suppress antitumour immunity." (PMID 34956172, 2021). "Total CD3+ T-cells, as well as cytotoxic CD8+, helper CD4+, and regulatory FOXP3+ T-cells were evaluated in the stromal and intra-epithelial compartments in tumor samples before and after NACT." (PMID 32852603, 2021). "Because CD4, FOXP3+ T cells tend to aggregate in tumors, qPCR showed variability depending on the tumor section used so we confirmed the decrease in FOXP3 mRNA expression in T cells sorted from tumors (p = 0.0072)." (PMID 34638488, 2021). "We previously characterized three distinct immune subtypes in PDAC, with over 50% of cases displaying an “immune-escape” phenotype poor in effector T cells but enriched in FOXP3+ Tregs and displaying high levels of tumor budding." (PMID 33806316, 2021). "In the present study, we investigated the associations of FoxP3+ Tregs and IDO+ stromal immune and tumor cells with prognostic factors and survival in CM." (PMID 34051744, 2021). "Another study indicated that Foxp3 in the tumor-infiltrating Treg cells serves as the immunosuppressive molecule to T-cell proliferation." (PMID 34820403, 2021). "There is still evidence indicates the correlation between PTEN loss on tumor cells and elevation of immunosuppressive markers like IDO1, FOXP3, CCL2, CSF1 ect.." (PMID 33874915, 2021). "These include an increase in CD8+ T-cells and effector memory T cells (CD44+ CD8+ CD62L+) and a decrease in Treg cells (CD4+ CD25+ Foxp3+) and M2 macrophages in the tumor microenvironment." (PMID 34360802, 2021). "It indicates that exosomal mutant KRAS DNA leads to this conversion, and it is further confirmed by the enrichment of FoxP3+ Tregs in tumor tissues from mutant KRAS patients, compared to the WT KRAS controls." (PMID 34616851, 2021). "Next, flow cytometric analysis showed that the frequency of tumor-infiltrating IL-21+CD4+ T cells positively correlated with that of FOXP3+CD25+CD4+ T cells, which supported our immunohistochemical results." (PMID 34026621, 2021). "The ratio of proliferating Foxp3+/CD8+ was significantly higher in HR+ as compared to HR− tumours (2.29 vs 1.33, P = 0.004)." (PMID 33742063, 2021).
tumor (continued). "All samples were stained with a sequential IHC workflow that included a panel of six antibodies for T cells subtyping (CD3, CD4, CD8 and Foxp3), proliferation (Ki67) and tumour recognition (cytokeratin) plus hematoxylin for counterstaining." (PMID 33742063, 2021). "It is now well substantiated that FOXP3-expressing Treg cells not only inhibit aberrant immune response against self-antigens but also suppress anti-tumor immune response." (PMID 34917120, 2021). "To explore the association between tumor-infiltrating T lymphocyte populations with CRC prognosis, we determined the infiltration of CD3+, CD8+, or FoxP3+ T lymphocytes within the tumor, tumor margins, and in the normal adjacent tissue by immunohistochemistry." (PMID 34440038, 2021). "At the same time, the initial, during the early, precryosurgical phase of imiquimod treatment, increased infiltration of the tumor by Treg (Foxp3+) cells is reversed." (PMID 34698134, 2021). "In mouse tumor models and primary human tumors, analysis of DNA methylation patterns at the Foxp3 locus as well as functional studies revealed that Treg cells infiltrating in the TME mainly corresponded to nTreg and not iTreg cells." (PMID 34262562, 2021). "As a result, the CD8/FOXP3 ratio was significantly higher in MNT cases than in MNCA cases in both the tumor nest (P = 0.041) and peri‐tumoral lymphoid stroma (P = 0.046)." (PMID 33819365, 2021). "Some authors have suggested that distinct subpopulations of tumor-infiltrating Foxp3 (+) T cells contribute in opposing ways to the determination of CRC prognosis." (PMID 33919941, 2021). "CSF-1R+ carcinoma cells are significantly associated with stromal tumor-infiltrating lymphocytes; intraepithelial lymphocytic infiltrates expressing CD8, FOXP3, TIM3, LAG3, and PD-1; and PD-L1+ carcinoma cells (p < 0.001)." (PMID 34830923, 2021). "Taken together, our data show that the location and type of tumor-infiltrating lymphocytes are associated with the pathogenesis of CRC; however, only high FoxP3+ T lymphocyte infiltrations are inclined to indicate favorable prognosis." (PMID 34440038, 2021). "Overall, NACT was associated with significant increases in anti-tumor CD8+, CD3+ TILs, and CD68+ macrophages and had a more variable impact on suppressive FOXP3+ TILs and CD163+ macrophages." (PMID 32852603, 2021). "Recent work on tumor immune microenvironment demonstrated that WHO grading in meningioma negatively correlates with the proportion of CD4+, CD8+, and PD-1+ lymphocytes, along with increased numbers of Treg (FOXP3+) cells in the tumor." (PMID 33611710, 2021). "Studies have demonstrated that accumulation of FOXP3+ regulatory T-cells in EOC limits anti-tumor immunity and favors tumor cell growth, thereby reducing patient survival." (PMID 32852603, 2021). "FoxP3 is an important marker for Treg cells, and the expression of FoxP3+Treg is associated with the immune escape of tumor cells, while HIF‐1α can upregulate molecules that attract FoxP3+Treg." (PMID 34387383, 2021). "Two-way ANOVA revealed a significant interaction between age and stress status (p=0.02) in tumor CD4+FoxP3+ cells number." (PMID 34604038, 2021). "CD4+ regulatory T (Treg) cells, dependent upon the transcription factor Foxp3, contribute to tumour immunosuppression but are also required for immune homeostasis." (PMID 33838058, 2021). "Conclusively, the net effect of cryosurgery during imiquimod treatment of BCC is an abrupt increase in the CD3+/Foxp3+ ratio at the tumor site." (PMID 34698134, 2021). "The study identified an upregulation of Lnc-EGFR in Tregs and was well-correlated with the expression of EGFR/Foxp3 and tumor size, but negatively correlated with IFN-γ expression." (PMID 34303380, 2021). "The higher Tregs levels in tumor tissues indicated a worse prognosis and the FOXP3+ Tregs/CD4+ T cell ratio was an independent prognostic factor for OS." (PMID 33545975, 2021).
tumor (continued). "In breast and CRC, a high tumor infiltration by CCR8+FOXP3+ Tregs correlates with a significantly shorter patient overall survival (OS)." (PMID 33924428, 2021). "Similar to the findings in previous reports, we observed an increased proportion of Tregs as well as a significantly higher expression of FoxP3 in tumor SN as compared to the corresponding NSN." (PMID 34458377, 2021). "We observed that the median density of immune subsets varied greatly across the untreated tumor cohort, particularly for B-cells, FoxP3 T-cells and CD8 T-cells." (PMID 34987518, 2021). "It has been found that MK-4166, a human GITR agonist, can reduce the expression of Foxp3 mRNA in human tumor infiltrating Tregs." (PMID 33557842, 2021). "The tumor tissue-infiltrated CD4+ FOXP3+ Treg were also increased after CAF depletion, which reduced tumor response to gemcitabine treatment via cytotoxic T-lymphocyte-associated protein (CTLA)-4-induced immunosuppression." (PMID 34868982, 2021). "In both FAP and CRC patients, increased numbers of CD4+Foxp3+ Tregs have been shown in tumor-draining lymph nodes and tumor sites; the function of Treg cells remains controversial in both FAP and CRC." (PMID 33628741, 2021). "Tim-3 also participates in the progression of tumor by regulating Tim-3+ Foxp3+ Treg cells and innate immune cells." (PMID 34631560, 2021). "The prognostic role of tumor-infiltrating FoxP3+ T lymphocytes in patients with HNSCC is controversial." (PMID 35087741, 2021). "For tumor-infiltrating lymphocytes (TILs), subgroup analysis demonstrated FOXP3 and PD-1, PD-L1, lymphocyte activation gene-3, CD3, CD4, or CD8 double positive were significantly correlated with longer RFS." (PMID 34006632, 2021). "Despite this, we were not able to find any statistically significant alterations in the overall survival of patients, even though high infiltrations of FoxP3+ T lymphocytes in the tumor margin resulted in an increased overall survival of 14 months." (PMID 34440038, 2021). "Accumulation of Foxp3+ regulatory T (Treg) cells in the tumor often represents an important mechanism for cancer immune evasion and a critical barrier to anti-tumor immunity and immunotherapy." (PMID 34798898, 2021). "This group observed that stromal FoxP3/CD3 ratio, tumor IL-12Rβ2, and tumor IL-7R were associated with recurrence." (PMID 34880292, 2021). "Another key finding was the dichotomy determined between frequencies of FoxP3+ CD4+ and FoxP3+ CD4-CD8- cells in blood compared to tumor where frequencies of FoxP3+ cells were significantly higher in tissue than detected in circulation." (PMID 34926643, 2021). "In the luminal A subtype, high numbers of CD3+ and FOXP3+ cells were associated with reduced RFS, and FOXP3+ cells from the tumor margins were also related to reduced DSS." (PMID 34076969, 2021). "The activatory/repressing role of splicing events on the neoplastic development/progression has been studied recently in different neoplasms, including alternative splicing of FOXP3." (PMID 34768829, 2021). "This study aimed to investigate the immune microenvironment, including the distribution and cell density of CD8 (+) T cells, FOXP3 (+) T cells and PD‐1 (+) T cells and PD‐L1 expression in tumor cells from patients with MNT and MNCA." (PMID 33819365, 2021). "Upon exposure to CVA21, there was a trending decrease in regulatory T-cells (FoxP3+/FoxP3-) that typically impede tumor responses." (PMID 34503272, 2021). "Higher rates of CD8+, FOXP3+, and PD-1+ TILs in advanced-stage specimens and fewer TILs in the tumor microenvironment of early-stage UC were noticed." (PMID 35052695, 2021). "Disruption of the PTEN/Akt/Foxo3a pathway through inhibition of PTEN results in Treg instability and the transitioning of suppressive Foxp3+ Tregs to proinflammatory ex-Tregs, leading to a more immunogenic microenvironment and substantial tumor regression." (PMID 34394124, 2021).
tumor (continued). "For checkpoints expressed on tumor cells, the subgroup analysis of combing FOXP3 on TILs as well as PD-L1 level on SCLC cells revealed a significant prognostic value as well (p=0.017)." (PMID 34006632, 2021). "FOXP3 expression in cancer is usually associated with tumor-promoting CD4 T cells and the suppression of anti-tumor immune cells, such as effector CD8 T cells." (PMID 34638488, 2021). "Crucially, when we perform the same analyses for the tumor margins, we found that the presence of high CD3+, CD8+, or FoxP3+ T lymphocyte infiltrates were associated with TNM stages I-II, non-invasion of lymph nodes, and normal CEA levels." (PMID 34440038, 2021). "Accordingly, targeting ubiquitin-specific protease (Usp) 7, which controls Treg function primarily by stabilizing expression and promoting multimerization of Tip60 and Foxp3, limits tumor progression." (PMID 34880761, 2021). "A meta-analysis comprising 15,512 patients demonstrated that the prognostic role of FOXP3 was highly influenced by the tumor site and tumor stage." (PMID 34201050, 2021). "A recent study showed that HNSCC with high tumor infiltration level of FoxP3+ Tregs more often exhibited better disease-free survival." (PMID 33526991, 2021). "Then it came to a conclusion that the Foxp3+/CD4+ TIL ratio in tumor tissue was an independent prognostic factor for HCC." (PMID 34566989, 2021). "Another study encompassing 104 EOC patients reported that FoxP3+ Treg cells suppressed tumor-specific T cells and induced the growth of tumors in vivo." (PMID 33819196, 2021). "Expression levels of epigenetic regulators and FoxP3, an inflammatory tumor suppressor, were determined." (PMID 34900746, 2021). "While these studies have relied on FoxP3+ Tregs, others have included additional parameters, including FoxP3 expression in tumor cells." (PMID 34141625, 2021). "The induction of CD4+CD25+Foxp3+Treg cells appears to contribute to the formation of immune-suppressive conditions that facilitate tumor immune escape mechanisms." (PMID 33754058, 2021). "FOXP3 showed punctate and moderately positive infiltrating distribution on the nucleus of Tregs in the tumor stroma." (PMID 34307135, 2021). "The proportion of CD4+Foxp3+ Tregs in tumor infiltrating lymphocytes (TIL) of CRC was dramatically higher than that of paired controls." (PMID 34095111, 2021). "First, the prognostic value of the FOXP3 level on TILs on clinical outcomes can vary with tumor types, histological grade, as well as molecular subtype." (PMID 34006632, 2021). "Next, we focused on the IL-2/STAT5 signaling pathway, which plays important roles in both the stability of Foxp3 expression and the expansion of Foxp3+ Tregs even in the tumor microenvironment." (PMID 34248973, 2021). "Further explorative analysis revealed that tumors having a low CD8 T-cell ratio demonstrated a higher proportion of FoxP3 T-cells in tumor." (PMID 34987518, 2021). "To expand the understanding of the correlations between IL-21, PD-L1, and Tregs in the tumor microenvironment and their prediction of disease prognosis, we detected the expression of IL-21, PD-L1, and FOXP3 in 102 newly diagnosed HNSCC patients." (PMID 34026621, 2021). "There was a significant increase in the number of CD4+ T cells and Foxp3 expressing cells in the lungs of this mouse that rejected the tumor." (PMID 34142056, 2021). "FoxP3+, the most representative marker of Treg cells, plays a critical role in immune tolerance and the suppression of anti-tumor immunity." (PMID 34654443, 2021). "A significant increase in the tumor infiltrating CD8 T cells in the CA-170 in combination with cyclophosphamide group led to a favorable tumor suppressive CD8 T cell: FoxP3 ratio, thus accounting for the enhanced efficacy in this group." (PMID 34103659, 2021). "Application of TREM-1 signaling inhibitor GF9 statistically decreased CCR6+Foxp3+ Tregs infiltration, increasing the therapeutic efficacy of ICBs, as a result postponed tumor progression." (PMID 34095111, 2021).